SNORD114-18 (small nucleolar RNA, C/D box 114-18)
Synonyms: 14q(II-18)
Gene: Small nucleolar RNA gene on chromosome 14 (100,975,825 to 100,975,896, forward strand). Ensembl gene ENSG00000202142.
Gene Ontology:
Biological process: RNA processing
Cellular component: nucleolus
Homologues: Orthologues: chimpanzee SNORD114-18 (94% identical), macaque SNORD114-18 (88% identical). Paralogues in human: SNORD114-10 (88% identical), SNORD114-21 (85% identical), SNORD114-23 (85% identical), SNORD114-3 (85% identical), SNORD114-26 (83% identical), SNORD114-28 (83% identical), SNORD114-22 (82% identical), SNORD114-9 (82% identical), SNORD114-1 (81% identical), SNORD114-13 (81% identical), SNORD114-15 (81% identical), SNORD114-25 (81% identical), and 26 more.